RNU1-96P (RNA, U1 small nuclear 96, pseudogene)
Gene: Small nuclear RNA gene on chromosome 3 (27,513,871 to 27,514,032, forward strand). Ensembl gene ENSG00000201033.
Homologues: Orthologues: macaque U1 (99% identical), chimpanzee U1 (83% identical), guinea pig U1 (65% identical). Paralogues in human: RNU1-1 (84% identical), RNU1-2 (84% identical), RNU1-27P (84% identical), RNU1-28P (84% identical), RNU1-3 (84% identical), RNU1-4 (84% identical), RNVU1-18 (84% identical), RNVU1-29 (84% identical), U1 (84% identical), RNU1-89P (83% identical), RNVU1-1 (83% identical), RNVU1-28 (83% identical), and 134 more.